PTH (parathyroid hormone)
Diseases named in the same sentence as PTH in open-access papers (continued):
Sharing a sentence is not in itself a finding about the gene and the disease.
osteoporosis (continued). "However, other studies have shown that excess weight in children is associated with elevated levels of leptin and parathyroid hormone (PTH), both of which may enhance bone resorption and increase the risk of osteoporosis and fractures." (PMID 40566375, 2025). "Since excessive levels of circulating parathyroid hormone (PTH) increase osteoclastic activity and accelerate bone resorption, it might seem paradoxical that PTH can also be used as a treatment modality for diseases with bone loss, such as osteoporosis." (PMID 39625374, 2024). "Our study suggested that the combination of PTH and propranolol may offer new possibilities for effectively treating systemic bone loss and reducing the risk of subsequent fractures in patients with osteoporosis." (PMID 38514644, 2024). "In recent years, with the side effects caused by the application of PTH drugs, biphosphonate drugs, and calmodulin drugs, people have carried out more in-depth research on the mechanism of osteoblast differentiation, and are actively looking for natural compounds for the treatment of osteoporosis." (PMID 39468464, 2024). "Elevated PTH concentrations may indicate an increased risk of osteoporosis." (PMID 38017527, 2023). "In addition, the 25‐hydroxyvitamin D3 of the younger daughter was lower than normal values, which may have contributed to the elevated PTH level, suggesting a risk for osteoporosis occurrence." (PMID 36669868, 2023). "In addition, we performed subgroup analysis stratified by age, sex, hypertension, DM, and obesity, to examine the correlation between serum 25(OH)D and the risk of anemia, after adjusting for variables, including PTH, history of osteoporosis, and number of days with arthritis or rheumatism." (PMID 36311487, 2022). "In addition, hyperparathyroidism, caused by excessive secretion of PTH from the parathyroid glands and characterized by elevated serum levels of calcium and PTH, often results in increased bone resorption and a higher risk of osteoporosis and fracture." (PMID 35379274, 2022). "Therefore, dietary Mg deficiency may affect osteoporosis by altering the balance between vitamin D metabolite and PTH." (PMID 35711538, 2022). "High serum PTH concentrations cause the mobilization of bone calcium and abnormal deposition of calcium and phosphorus in soft tissues, such as blood vessels, skin, and heart valves, leading to osteoporosis, bone pain, fractures, severe vascular sclerosis, and pruritus, and thus a poor prognosis." (PMID 36531501, 2022). "Furthermore, antagonizing miR‐19a/b augments the gain in bone mass by PTH and restores bone loss in mouse models of osteoporosis in a dual mode of action by supporting bone formation and decreasing receptor activator of NF‐κB ligand (RANKL)‐dependent bone resorption." (PMID 36193848, 2022). "In addition, higher serum creatinine, β-CTX and PTH and lower 25(OH)D levels may be associated with osteoporosis." (PMID 33315972, 2020). "A concomitant rise in PTH and PTHrP at the end of pregnancy may pose a substantial burden on the maternal skeleton and could explain some of the cases with pregnancy-associated osteoporosis." (PMID 29641551, 2018). "Persistent excess of PTH is responsible for increased bone resorption and reduction of calcium deposition on bone tissue, leading to a pathological loss of cortical and trabecular bone and early osteopenia/osteoporosis with risk of fragility fractures both in sporadic PHPT and MEN1-related PHPT." (PMID 30364322, 2018). "Intermittent administration of parathyroid hormone (PTH) 1–34 has emerged as a pivotal therapeutic approach for osteoporosis, primarily because of its strong anabolic effects on bone metabolism." (PMID 41432314, 2026). "PTH, regulating calcium and phosphorus metabolism and stimulating bone formation, is crucial in osteoporosis treatment." (PMID 40217244, 2025). "It helps prevent osteoporosis and cardiovascular complications by regulating parathyroid hormone (PTH) levels." (PMID 40234287, 2025).
osteoporosis (continued). "On the other hand, antagonizing miR17 ~ 92 with an anti-miR17-92 oligo-augmented PTH-induced bone gain and restored bone mass in a mouse model of osteoporosis, implicating an inhibitory role of miR17 ~ 92 in PTH-mediated bone formation." (PMID 39751939, 2025). "The strongest evidence in the literature for medical treatment of osteoporosis in patients with FFPs is reported for the use of parathyroid hormone (PTH)." (PMID 40725815, 2025). "These dual effects are important when considering the potential applications of PTH in bone repair, particularly for treating osteoporosis and managing fractures." (PMID 40136530, 2025). "Data covering a five-year period (2018–2023) were analyzed to examine the sales trends of osteoporosis medications, including bisphosphonates, selective estrogen receptor modulators (SERMs), parathyroid hormone analogs, denosumab, romosozumab, and others." (PMID 40428763, 2025). "Intermittent (hyper or hypo) secretion of serum parathormone (PTH) causes primary hyperparathyroidism (PHPT), which is an asymptomatic endocrinal disorder resulted in osteoporosis of trabecular and cortical bones." (PMID 40496565, 2025). "Nowadays, pharmacological modalities for osteoporosis, such as bisphosphonates, antibodies, parathyroid hormone (PTH)-related peptides, and teriparatide, exhibit limitations in their therapeutic efficacy and are linked with consequential side effects." (PMID 40564050, 2025). "The current prescription of parathyroid hormone (PTH)-based-anabolic drugs for the treatment of osteoporosis, for instance, is limited by factors such as high cost and risk of osteosarcoma." (PMID 39806388, 2025). "PTH agents, which represent the only anabolic agents approved for osteoporosis prior to April 2019, increase both bone formation and resorption." (PMID 40428763, 2025). "A variety of agents have been utilized for the treatment of osteoporosis, including bisphosphonates, calcitonin, estrogen, parathyroid hormone, selective estrogen receptor modulators (SERMs)." (PMID 40171106, 2025). "We demonstrated that bisphosphonates, PTH analogs, denosumab, and sclerostin inhibitors can reduce clinical fracture risk in CKD patient’s osteoporosis but with low to very low confidence of evidence." (PMID 40599806, 2025). "Numerous studies have explored the efficacy and safety of AODs, including bisphosphonates, denosumab, and PTH analogs, for treating osteoporosis in the general population, postmenopausal women, and patients with different CKD stages." (PMID 40599806, 2025). "While mean levels of all evaluated bone biomarkers were normal, PTH and sBTMs were significantly lower in post-polio patients with osteoporosis compared to controls, indicating reduced bone turnover." (PMID 40547530, 2025). "In the pursuit of safer osteoporosis treatments, we investigated R25CPTH, a PTH variant wherein the native arginine at position 25 is substituted by cysteine." (PMID 40153305, 2025). "In specific, PTH levels should be kept in the upper normal limit to avoid either hypercalciuria and/or nephrocalcinosis because of excessive PTH suppression or osteoporosis from long-standing, insufficient inhibition of PTH." (PMID 40177730, 2025). "Intermittent PTH exposure stimulates anabolic osteoblastic bone formation and is indeed used for the treatment of osteoporosis." (PMID 40423237, 2025). "Teriparatide, a recombinant human parathyroid hormone (PTH) (1–34 amino acid receptor-binding fragment), is considered a potent medication for osteoporosis therapy." (PMID 40461584, 2025). "Our findings indicate that the inclusion of olive oil in the diet of rats that have undergone ovariectomy can protect against osteoporosis by regulating the levels of PTH and E2 hormones." (PMID 40125318, 2025).
osteoporosis (continued). "Higher mean PTH levels in the blood were detected in patients reporting urinary tract stones (356.90 pg/mL vs. 296.42 pg/mL; p < 0.05), osteoporosis (356.03 pg/mL vs. 297.64 pg/mL; p < 0.05), and cholelithiasis (357 pg/mL vs. 298.52 pg/mL; p < 0.05)." (PMID 39941666, 2025). "Teriparatide, a synthetic analog of parathyroid hormone, is conventionally utilized for osteoporosis and bone defect management." (PMID 40176894, 2025). "Osteoporosis treatment modalities include bisphosphonates, monoclonal antibodies, parathyroid hormone (PTH), and abaloparatide." (PMID 40153574, 2025). "The recent increase in its incidence is largely due to routine blood calcium testing and parathyroid hormone (PTH) measurements in osteoporosis evaluations." (PMID 41001160, 2025). "While anabolic agents that increase bone formation, such as parathyroid hormone (PTH), have aided in the management of osteoporosis, patients still experience adverse side-effects along with variations in therapeutic response." (PMID 41323638, 2025). "The systemic effects, like headache and nausea, have also been described in other studies with PTH analogs used in osteoporosis treatment, such as teriparatide or abaloparatide, and are thought to be a class effect." (PMID 40709359, 2025). "The main drug classes used to treat osteoporosis are bisphosphonates, selective estrogen receptor modulators (SERMs), parathyroid hormone (PTH) analogs, RANK–ligand inhibitors, and sclerostin inhibitors." (PMID 41374050, 2025). "In conclusion, when PHPT is suspected based on elevated serum PTH and calcium levels, osteoporosis, and other clinical indicators, we should keep in mind the possibility of an ectopic parathyroid adenoma." (PMID 40709121, 2025). "This study was designed to assess the impact of short-term intermittent PTH treatment on early peri-implant bone and soft tissue regeneration in a rat model of osteoporosis." (PMID 40507663, 2025). "Parathyroid hormone (PTH) is a key regulator of this homeostasis and along with its analogs has been used to treat osteoporosis, however its use is limited to an “anabolic window”." (PMID 40609791, 2025). "Conversely, in osteoporosis induced by chronic obstructive pulmonary disease (COPD) and parathyroid hormone (PTH), a deficiency in IL-17A reduces bone loss by decreasing osteoclast activity and RANKL expression." (PMID 40248692, 2025). "Parathyroid hormone (PTH) regulates serum calcium and phosphate through its actions in bone and kidney and is used to increase bone in osteoporosis treatment." (PMID 40694420, 2025). "A negative association was also found between serum levels of the studied vitamin D form and bone turnover markers and PTH in a group of women with osteopenia and osteoporosis." (PMID 40149488, 2025). "Third, PM2.5 exposure has been reported to contribute to osteoporosis through endocrine disruption, particularly affecting estrogen, testosterone, and parathyroid hormone levels." (PMID 41049427, 2025). "Parathyroid hormone (PTH) is one of a few anabolic drugs approved by the FDA to restore bone structural integrity and to reduce fracture risk in people with osteoporosis." (PMID 40668360, 2025). "Postoperatively, osteoporosis treatment was changed to the administration of PTH preparations in 6 patients." (PMID 40533679, 2025). "This was a retrospective study of patients prescribed parathyroid hormone analogs from a single osteoporosis clinic from 2017 to 2022." (PMID 40416275, 2025). "Current osteoporosis treatments primarily focus on inhibiting bone resorption (e.g., bisphosphonates) or modestly enhancing bone formation (e.g., parathyroid hormone analogs)." (PMID 41203627, 2025). "Possible mechanisms suggested include the promotion of PTH secretion and bone metabolism by a drop in serum calcium or the direct promotion of bone modeling by denosumab, as observed in primate models of osteoporosis." (PMID 40177730, 2025).
osteoporosis (continued). "The results of the study on the correlation between osteoporosis-related hormones and bone mineral density showed that the level of serum PTH was negatively correlated with bone mineral density, which allowed early detection of osteoporosis." (PMID 41030850, 2025). "In Chinese postmenopausal women with osteopenia and osteoporosis, higher serum levels of 25-hydroxyvitamin are associated with lower levels of BTMs - specifically β-CTX, osteocalcin, and PTH." (PMID 40854969, 2025). "Forty-six patients with serum PTH levels exceeding 70 pg/mL, ten patients with renal impairment, seven with current osteoporosis treatment, and nine patients denying participation in the study were excluded." (PMID 40461584, 2025). "In patients with osteoporosis, a disorder of calcium/parathyroid hormone regulation, the mean blood concentrations of calcium or parathyroid hormone remained unchanged compared to that in controls." (PMID 39324113, 2024). "Other less common osteoporosis treatments, such as testosterone, calcitonin, and PTH analogs, operate through mechanisms distinct from bisphosphonates [3•, 8]." (PMID 38372871, 2024). "Further evaluations of osteoporosis can involve measurements of urinary N-telopeptide and normal laboratory values of phosphorus, calcium, vitamin D, parathyroid hormone, and alkaline phosphatase." (PMID 38792583, 2024). "In recent years, osteoporosis treatment has mainly comprised antiresorptive drugs (bisphosphonates, strontium salts) and bone anabolic compounds [parathyroid hormone peptides PTH (1-84 or 1-34)]." (PMID 38464734, 2024). "BMP-7, a member of the BMP family, has demonstrated remarkable potential in bone fracture repair and can induce osteoblast differentiation even more effectively than PTH hormone, a widely used therapeutic alternative for osteoporosis treatment." (PMID 38540737, 2024). "Teriparatide, an osteoanabolic agent, is a biosynthetic analogue of the 1-34 amino acids of human parathyroid hormone (PTH) used for the treatment of osteoporosis." (PMID 38933734, 2024). "In this study, we compared bone regeneration using different grafts in an osteoporosis model and investigated the efficacy of directly applying PTH to the defect site." (PMID 38672175, 2024). "Teriparatide, a recombinant parathyroid hormone, is pivotal in osteoporosis treatment, particularly in post-surgical recovery for hip fractures." (PMID 38614984, 2024). "More importantly, Clec11a has high therapeutic potential for treating various bone diseases and can enhance the therapeutic effects of the parathyroid hormone against osteoporosis." (PMID 39188913, 2024). "Previous studies have used PTH in combination with bisphosphonates to achieve better osteogenesis and reduce the amount of PTH in the treatment of osteoporosis." (PMID 38357710, 2024). "The PTH1R is activated by parathyroid hormone–related protein (PTHrP) and by parathyroid hormone (PTH) of which an analog (teriparatide) is approved for the treatment of osteoporosis." (PMID 38984948, 2024). "On the other hand, we found that FGF, in addition to PTH, is widely expressed in the human bone matrix and plays a role in regulating the formation and development of osteoporosis." (PMID 39268461, 2024). "Recent years have brought notable progress in osteoporosis treatments, including bisphosphonates, Selective Estrogen Receptor Modulators (SERMs), calcitonin, and parathyroid hormone (PTH) and its analogs, along with the newer Sclerostin inhibitors." (PMID 38841589, 2024). "Among the TDT patients, only the PTH level was significantly correlated with the rate of osteoporosis." (PMID 38606231, 2024). "Teriparatide (TP) is a biosynthetic analogue of the first 34 N-terminal amino acids of parathyroid hormone (PTH), used in the treatment of osteoporosis." (PMID 38933734, 2024). "Spearman correlation analysis unveiled negative associations between serum 25(OH)D concentrations and both BTMs and PTH within both the osteopenia and osteoporosis group." (PMID 38268673, 2024).
osteoporosis (continued). "Drugs such as bisphosphonates (BPs), denosumab, vitamin preparations, calcium preparations, parathyroid hormone (PTH) agents, and anti-sclerostin antibodies are used to treat osteoporosis." (PMID 38376670, 2024). "Excessive secretion of PTH can lead to hyperparathyroidism, increase of blood calcium, secondary osteoporosis, urinary stone and other diseases." (PMID 38840246, 2024). "Patients with osteoporosis will have normal levels of serum calcium, phosphate, alkaline phosphatase, and PTH, whereas abnormalities in at least one of these laboratory values are commonly seen in osteomalacia." (PMID 39301310, 2024). "Some supplements, such as calcium, vitamin D or K, as well as drugs such as selective estrogen receptor modulators, calcitonin, parathyroid hormone, other estrogen analogs, bisphosphonates, and hormone replacement therapy, are used to treat osteoporosis." (PMID 37002419, 2024). "Treatments for osteoporosis include bisphosphonates, monoclonal antibodies, parathyroid hormone (PTH), and abaloparatide." (PMID 38334917, 2024). "In this study, we applied the method of absorbing parathyroid hormone (PTH), a treatment for osteoporosis, into graft materials." (PMID 38672175, 2024). "Common clinical therapies for immune suppression or osteoporosis include glucocorticoids and parathyroid hormone-based therapies, respectively." (PMID 39092287, 2024). "An early study of the use of PTH to treat osteoporosis showed that when given intermittently, bone formation exceeded bone resorption in the first 6–18 months of the treatment." (PMID 38372871, 2024). "Pathophysiologically, CKD-related osteoporosis involves elevated PTH levels, the retention of phosphate, irregular calcium handling, vitamin D deficiency, soft tissue calcification, and decreased bone formation and turnover." (PMID 39697967, 2024). "In this context, the shared opinion holds that lowering serum PTH levels is critical in the treatment of osteoporosis." (PMID 39438361, 2024). "Osteoporosis treatments include anti-resorptive therapies (e.g., bisphosphonates) and bone formation therapies (e.g., intermittent PTH)." (PMID 38503736, 2024). "The first anabolic agent used to treat osteoporosis was teriparatide (TP), a human recombinant parathyroid hormone (PTH)." (PMID 39685632, 2024). "Mg participates in the pathogenesis of osteoporosis by affecting the regulation of parathyroid hormone and vitamin D levels to affect the RANK/RANKL/OPG axis." (PMID 38904051, 2024). "The experts believe that efficient treatment for patients with osteoporosis should include calcium and vitamin D supplementation to achieve adequate levels that are able to inhibit the parathyroid hormone and bone resorption." (PMID 39438361, 2024). "The predictive power for further fractures was 10.7% higher adding osteosarcopenia, BMI and parathyroid hormone levels to standard assessment parameters osteoporosis, age and the status of previous fractures." (PMID 39513358, 2024). "Current research on osteoporosis focuses on the cells inside the bone marrow cavity, which has led to the development of drugs such as bisphosphonates, denosumab and parathyroid hormone to treat osteoporosis." (PMID 39622781, 2024). "The use of daily injections in this study was intended to simulate intermittent PTH therapy, a well-established clinical approach for managing osteoporosis and enhancing bone regeneration." (PMID 39625374, 2024). "In this review, we not only underscore the critical function of PTH1R in bone remodeling and bone physiology but also elucidate the therapeutic potentials of PTH and PTHrP in the management of osteoporosis." (PMID 38474370, 2024). "PTH-derived agents are used as bone anabolic therapies and importantly, these agents have proven effective in the treatment of glucocorticoid-induced osteoporosis." (PMID 39092287, 2024).